MFSD1 (major facilitator superfamily domain containing 1)
Description:
Lysosomal dipeptide uniporter that selectively exports lysine, arginine or histidine-containing dipeptides with a net positive charge from the lysosome lumen into the cytosol. Could play a role in a specific type of protein O-glycosylation indirectly regulating macrophages migration and tissue invasion. Also essential for liver homeostasis (By similarity).
Synonyms: SMAP4; UG0581B09; Minerva; SLC72A1; FLJ14153
Tractability: Antibody: UniProt predicts a signal peptide or a membrane-spanning region; the Human Protein Atlas places it where antibodies can reach. PROTAC: ubiquitination databases record sites on it; its protein half-life has been measured.
Gene: Protein-coding gene on chromosome 3 (158,732,198 to 158,829,719, forward strand). Ensembl gene ENSG00000118855.
Subcellular location: Lysosome membrane
Subcellular location (Human Protein Atlas): Plasma membrane; Cytosol
Gene Ontology:
Molecular function: dipeptide uniporter activity; protein homodimerization activity; transmembrane transporter activity
Biological process: dipeptide transmembrane transport from lysosomal lumen to cytosol; protein localization to lysosome; protein stabilization; dipeptide transmembrane transport; transmembrane transport
Cellular component: lysosomal membrane; lysosome
Genetic constraint (gnomAD): Loss-of-function variants: 15 observed, 22.5 expected, observed/expected ratio (o/e) 0.67, 90% interval 0.44 to 1.03. The upper end of that interval is the gene's LOEUF score, 1.03, which puts it in group 4 of 6, group 1 being the genes least tolerant of losing a copy. Missense variants: 318 observed, 359.67 expected, observed/expected ratio (o/e) 0.88, 90% interval 0.81 to 0.97. Synonymous variants: 137 observed, 135.66 expected, observed/expected ratio (o/e) 1.01, 90% interval 0.88 to 1.16.
Homologues: Orthologues: chimpanzee MFSD1 (99% identical), macaque MFSD1 (99% identical), rabbit MFSD1 (95% identical), pig MFSD1 (93% identical), dog MFSD1 (92% identical), mouse Mfsd1 (88% identical), rat Mfsd1 (87% identical), guinea pig MFSD1 (86% identical), tropical clawed frog mfsd1 (74% identical), zebrafish mfsd1 (57% identical), Drosophila melanogaster CG12194 (51% identical), Drosophila melanogaster mrva (50% identical), and 8 more. Paralogues in human: SLC71A2 (17% identical), SLC71A1 (16% identical), SLC75A1 (14% identical), SLC67A2 (14% identical), MFSD8 (13% identical), SLC61A1 (12% identical).
Diseases named in the same sentence as MFSD1 in open-access papers:
MFSD1 is named in the same sentence as 25 diseases in open-access papers, as found by Europe PMC text mining. Sharing a sentence is not in itself a finding about the gene and the disease. The quoted sentences say what the papers report.
breast carcinoma (2 papers, 2019 to 2022). "We achieved similar levels of shRNA knockdown of MFSD1 in two other murine tumor cell lines, 4T1 breast cancer and B16-BL6 melanoma." (PMID 35211397, 2022). "(C) Quantitation using Fiji of the colocalization of MFSD1-eGFP with the Golgi marker (GRASP65), early endosome marker (Rab5), late endosome marker (Rab7), and lysosome marker (LAMP1) in MC-38 colon carcinoma, B16-BL6 melanoma, LLC1 Lewis lung carcinoma, and 4T1 breast carcinoma cells." (PMID 30910009, 2019).
colon carcinoma (2 papers, 2019 to 2022). "Here, we identify a cell biological function regulated by MFSD1, namely, the recycling of β1 integrin from the endolysosomal system, utilizing a murine colon carcinoma cell line." (PMID 35211397, 2022). "We find MFSD1 localized to the endolysosomal system in colon carcinoma cells and fibroblasts, just as we have observed previously for its fly ortholog, Mrva, in macrophages." (PMID 35211397, 2022). "We prepared a murine colon carcinoma cell line MC-38 MFSD1kd stably expressing a shRNA which reduces MFSD1 expression by 75% compared with the levels in corresponding control cells expressing an nt-shRNA." (PMID 35211397, 2022). "(B) Confocal images of MC-38 colon carcinoma cells showing colocalization of MFSD1-eGFP (green) with the Golgi marker GRASP65 (red)." (PMID 30910009, 2019).
liver disease (2 papers, 2019 to 2020). "MFSD1 has been found to be tightly connected to Glycosylated Lysosomal Membrane Protein (GLMP) where the loss of MFSD1 causes severe liver disease in MFSD1-knockout mice." (PMID 32733888, 2020). "MFSD1-deficient mice develop a severe liver disease characterized by extravasation of erythrocytes, sinusoidal damage, loss of liver sinusoidal endothelial cells (LSECs) and finally signs of fibrosis." (PMID 31661432, 2019). "Mfsd1 knockout mice develop splenomegaly and severe liver disease." (PMID 31661432, 2019).
Splenomegaly (2 papers, 2019 to 2023). Abnormal increased size of the spleen. "It should be noted that Glmp KO mice, similar to Mfsd1 KO mice, suffer from splenomegaly." (PMID 31661432, 2019). "The Glmpgt/gt mouse lacks expression of a subunit of the MFSD1/GLMP lysosomal membrane protein transporter complex, is born normal, but soon develops chronic, mild hepatocyte injury, leading to slowly progressing periportal liver fibrosis, and splenomegaly." (PMID 37910485, 2023).
gastric tumors (1 paper, 2022). "We also screened data available on the Kaplan–Meier plotter page for the association of MFSD1 expression (mRNA gene chip) and the prognosis of lung, breast, and gastric tumor patients." (PMID 35211397, 2022). "MFSD1 expression levels correlate with the survival of patients with lung, breast, and gastric tumors, and downregulation of MFSD1 expression happens during early events of colon tumorigenesis." (PMID 35211397, 2022).
high blood pressure (1 paper, 2019). "Also, elevated levels of LDLRAD4, SLC9C2, and MFSD1 were observed in the patients with high blood pressure." (PMID 30547318, 2019).
lysosomal storage disease (1 paper, 2019). A metabolic disorder caused by mutations in proteins critical for lysosomal function, including lysosomal enzymes, lysosomal integral membrane proteins, and proteins involved in the post-translational modification and trafficking of lysosomal proteins. "The phenotype of Mfsd1 KO mice is complex and the liver phenotype did not resemble that observed in mouse models of lysosomal storage diseases." (PMID 31661432, 2019).
metastatic disease (1 paper, 2022). "However, to substantiate the role of MFSD1 during tumorigenesis and metastatic spread, further experiments with genetic tumor mouse models displaying metastatic disease are required." (PMID 35211397, 2022).
Obesity (1 paper, 2019). Accumulation of substantial excess body fat. "The present study discovered that five genes (A2BP1, TENM2, LDLRAD4, SLC9C2, and MFSD1) were associated with metabolic traits such as obesity and high blood pressures." (PMID 30547318, 2019). "Specifically, if any one of TENM2, A2BP1, LDLRAD4, SLC9C2, or MFSD1 was observed in the patients with periodontitis, obesity and blood pressure have to be treated simultaneously." (PMID 30547318, 2019). "Therefore, if any of TENM2, A2BP1, LDLRAD4, SLC9C2, and MFSD1 is detected in the patients with periodontitis, obesity and blood pressure have to be treated simultaneously." (PMID 30547318, 2019).
periodontitis (1 paper, 2019). An acute or chronic inflammatory process that affects the tissues that surround and support the teeth. "A total 10,268 SNPs of ten targeted periodontitis genes were analyzed among 2649 SNPs in five genes (TENM2, LDLRAD4, SLC9C2, MFSD1, and A2BP1), and their statistical differences (p < 0.05) are listed." (PMID 30547318, 2019).
triple-negative breast carcinoma (1 paper, 2022). An invasive breast carcinoma which is negative for expression of estrogen receptor (ER), progesterone receptor (PR), and human epidermal growth factor receptor 2 (HER2). "Refractory free survival of triple-negative breast cancer patients was significantly reduced in patients with low MFSD1 expression with a survival of the low expression cohort of 19.81 months compared with 55.2 months in the high expression cohort." (PMID 35211397, 2022).
cancer (3 papers, 2019 to 2022). A tumor composed of atypical neoplastic, often pleomorphic cells that invade other tissues. "Furthermore, downregulation of MFSD1 expression was observed during the early steps of tumorigenesis, and higher MFSD1 expression levels correlate with a better cancer patient prognosis." (PMID 35211397, 2022). "Thus, these experiments support the conclusion that for multiple types of murine cancer cell lines, MFSD1 suppresses metastasis in vivo." (PMID 35211397, 2022). "Thus, early reduction in MFSD1 expression might be beneficial for tumor cells to acquire hallmarks of cancer." (PMID 35211397, 2022).
tumor (3 papers, 2019 to 2024). "To date, it is still an open question how these specific dipeptides exported by MFSD1 contribute to the phenotypes observed in the MFSD1−/− mouse, in MFSD1−/− tumor cells, and during lymphocyte development and liver homeostasis." (PMID 38507452, 2024). "By employing two different tumor cell lines in an experimental metastasis, as well as a third in an orthotopic spontaneous metastasis setting, we observed that MFSD1 restrains metastatic spread." (PMID 35211397, 2022). "In sum, these experiments clearly demonstrate that MFSD1 suppresses the in vitro migration of multiple tumor cell types." (PMID 35211397, 2022). "In sum, we describe a requirement for endolysosomal MFSD1 in efficient β1 integrin recycling to suppress tumor cell dissemination." (PMID 35211397, 2022). "We describe here the involvement of the orphan solute carrier Major Facilitator Superfamily Domain-containing protein 1 (MFSD1) in the regulation of tumor cell migration." (PMID 35211397, 2022). "In tumor cells, the strongest MFSD1 staining co-localized with its accessory subunit GLMP in the Golgi apparatus." (PMID 35211397, 2022). "This increased migration was also observed upon MFSD1 knockdown in 4T1 and B16-BL6 tumor cell lines, supporting a role for MFSD1 in tumor cell migration across tumor cell types." (PMID 35211397, 2022). "To gain insight into the possible functions of MFSD1, we examined its subcellular location in tumor cells." (PMID 35211397, 2022). "Here, we show that MFSD1 in tumor cells restrains metastasis, decreases the rate of migration, and lowers the resistance to mechanical stress and starvation-induced apoptosis by reducing the activation index of β1 integrin through the recycling pathway." (PMID 35211397, 2022). "Supporting a role of MFSD1 during the entire metastatic cascade starting at the primary tumor, we observed an increased number of pulmonary metastases in mice injected with 4T1 MFSD1kd compared with control cells." (PMID 35211397, 2022). "In four metastasizing mouse tumor cell lines we find MFSD1 mainly in the Golgi, where O-glycosylation is known to occur." (PMID 30910009, 2019). "However, MFSD1 had a different effect on cell migration in the fly and the mammalian tumor cell system." (PMID 35211397, 2022). "In addition, given the published effects of MFSD1 involving endothelial cells, it will be of high interest to also investigate the contribution of stromal cell MFSD1 during tumor disease progression." (PMID 35211397, 2022). "Given the capacity of MFSD1 to regulate the invasive migration of macrophages in the fly embryo, we were interested in whether MFSD1 is involved in mammalian tumor cell migration." (PMID 35211397, 2022). "We hypothesize that the Golgi localization of MFSD1-eGFP in tumor cells might be due to tumor cell-specific retention in the Golgi apparatus." (PMID 35211397, 2022). "We aimed to study the effect of MFSD1 on tumor cell migration." (PMID 35211397, 2022). "Thus, we observed that MFSD1 stabilizes focal adhesions and the maturely N-glycosylated β1 integrin protein in MC-38 tumor cells." (PMID 35211397, 2022). "MFSD1 restrained migration in the three tumor cell lines we tested." (PMID 35211397, 2022). "Therefore, we analyzed the expression levels of MFSD1 during tumor formation." (PMID 35211397, 2022). "From these experiments, we conclude that most likely neither O- nor N-glycosylation is directly affected by MFSD1 in tumor cells." (PMID 35211397, 2022).
heart disease (1 paper, 2022). "The expression level of Mfsd1 could be affected by left heart disease in rats." (PMID 35055737, 2022).
MFSD1 also shares sentences with these, for which no sentence is quoted: melanoma (2 papers); clear renal cell carcinoma (1); colon adenocarcinoma (1); colorectal adenoma (1); colorectal carcinoma (1); colorectal tumor (1); Lewis lung carcinoma (1); liver fibrosis (1); lung adenocarcinoma (1); lung squamous cell carcinoma (1); sinusoidal obstruction syndrome (1).